SRPK1 (SRSF protein kinase 1)
Description:
Serine/arginine-rich protein-specific kinase which specifically phosphorylates its substrates at serine residues located in regions rich in arginine/serine dipeptides, known as RS domains and is involved in the phosphorylation of SR splicing factors and the regulation of splicing. Plays a central role in the regulatory network for splicing, controlling the intranuclear distribution of splicing factors in interphase cells and the reorganization of nuclear speckles during mitosis. Can influence additional steps of mRNA maturation, as well as other cellular activities, such as chromatin reorganization in somatic and sperm cells and cell cycle progression. Isoform 2 phosphorylates SFRS2, ZRSR2, LBR and PRM1. Isoform 2 phosphorylates SRSF1 using a directional (C-terminal to N-terminal) and a dual-track mechanism incorporating both processive phosphorylation (in which the kinase stays attached to the substrate after each round of phosphorylation) and distributive phosphorylation steps (in which the kinase and substrate dissociate after each phosphorylation event). The RS domain of SRSF1 binds first to a docking groove in the large lobe of the kinase domain of SRPK1. This induces certain structural changes in SRPK1 and/or RRM2 domain of SRSF1, allowing RRM2 to bind the kinase and initiate phosphorylation. The cycles continue for several phosphorylation steps in a processive manner (steps 1-8) until the last few phosphorylation steps (approximately steps 9-12). During that time, a mechanical stress induces the unfolding of the beta-4 motif in RRM2, which then docks at the docking groove of SRPK1. This also signals RRM2 to begin to dissociate, which facilitates SRSF1 dissociation after phosphorylation is completed. Isoform 2 can mediate hepatitis B virus (HBV) core protein phosphorylation. It plays a negative role in the regulation of HBV replication through a mechanism not involving the phosphorylation of the core protein but by reducing the packaging efficiency of the pregenomic RNA (pgRNA) without affecting the formation of the viral core particles. Isoform 1 and isoform 2 can induce splicing of exon 10 in MAPT/TAU. The ratio of isoform 1/isoform 2 plays a decisive role in determining cell fate in K-562 leukemic cell line: isoform 2 favors proliferation where as isoform 1 favors differentiation. Phosphorylates the N-terminus of ERC1.
Synonyms: SFRSK1
Tractability: Small molecule: a structure with a bound ligand is known; a high-quality ligand is known; it has a high-quality binding pocket; it belongs to a druggable protein family. Antibody: its Gene Ontology location is reachable by antibodies, with high confidence. PROTAC: ubiquitination databases record sites on it; its protein half-life has been measured; a small molecule that binds it is known.
Target class: CMGC protein kinase group; Enzyme; Kinase; Protein Kinase; CMGC protein kinase SRPK family
Chemical probes: JH-XI-05-01 (high quality), MSC1186 (high quality)
Gene: Protein-coding gene on chromosome 6 (35,832,966 to 35,921,342, reverse strand). Ensembl gene ENSG00000096063.
Subcellular location: Cytoplasm (Isoform 2); Nucleus; Nucleus matrix; Microsome; Cytoplasm (Isoform 1); Cytoplasm; Nucleus, nucleoplasm; Nucleus speckle; Chromosome
Subcellular location (Human Protein Atlas): Cytosol; Nucleoplasm; Plasma membrane
Pathways (Reactome):
Developmental Biology: Replacement of protamines by nucleosomes in the male pronucleus
Disease: Maturation of nucleoprotein
Gene Ontology:
Molecular function: ATP binding; magnesium ion binding; protein binding; protein serine kinase activity; protein serine/threonine kinase activity; RNA binding; protein kinase activity
Biological process: chromosome segregation; intracellular signal transduction; negative regulation of viral genome replication; positive regulation of viral genome replication; protein phosphorylation; regulation of mRNA processing; innate immune response; regulation of mRNA splicing, via spliceosome; RNA splicing; sperm DNA condensation; spliceosomal complex assembly
Cellular component: chromatin; chromosome; cytoplasm; cytosol; nuclear speck; nucleoplasm; nucleus; nuclear matrix
Genetic constraint (gnomAD): Loss-of-function variants: 34 observed, 59.35 expected, observed/expected ratio (o/e) 0.57, 90% interval 0.44 to 0.76. The upper end of that interval is the gene's LOEUF score, 0.76, which puts it in group 3 of 6, group 1 being the genes least tolerant of losing a copy. Missense variants: 501 observed, 655.51 expected, observed/expected ratio (o/e) 0.76, 90% interval 0.71 to 0.82. Synonymous variants: 222 observed, 236.7 expected, observed/expected ratio (o/e) 0.94, 90% interval 0.84 to 1.05.
Homologues: Orthologues: chimpanzee SRPK1 (99% identical), macaque SRPK1 (99% identical), rabbit SRPK1 (97% identical), dog SRPK1 (96% identical), pig SRPK1 (94% identical), rat Srpk1 (92% identical), mouse Srpk1 (91% identical), guinea pig SRPK1 (87% identical), tropical clawed frog srpk1 (65% identical), zebrafish srpk1b (64% identical), Drosophila melanogaster SRPK (48% identical), Caenorhabditis elegans spk-1 (46% identical), and 7 more. Paralogues in human: SRPK2 (60% identical), SRPK3 (51% identical), NLK (16% identical), CILK1 (16% identical), MAPK13 (16% identical), MAPK12 (15% identical), MAPK14 (15% identical), MAPK10 (15% identical), MAPK3 (15% identical), MAPK8 (15% identical), MAPK11 (15% identical), MAPK9 (15% identical), and 7 more.
Diseases named in the same sentence as SRPK1 in open-access papers:
SRPK1 is named in the same sentence as 95 diseases in open-access papers, as found by Europe PMC text mining. Sharing a sentence is not in itself a finding about the gene and the disease. The quoted sentences say what the papers report.
breast cancer (29 papers, 2007 to 2025). A primary or metastatic malignant neoplasm involving the breast. "Yet, in a recent report, the nuclear localization of SRPK1 was associated with cisplatin resistance of breast cancer cells." (PMID 33808326, 2021). "When they sub-categorized luminal breast cancer patients into luminal A and B, they found a significant association between SRPK1 overexpression and the more aggressive of the two luminal B subtype." (PMID 31861708, 2019). "It has been shown that disruption of SRPK1 expression by small interfering RNA increases apoptosis caused by cDDP in pancreatic, colon and breast cancer cell lines." (PMID 23236423, 2012). "Second, it has been recently shown that disruption of SRPK1 expression by siRNA increases apoptosis caused by cDDP in pancreatic, colon and breast cancer cell lines." (PMID 23236423, 2012). "Micro RNA-9 (miRNA-9) is under-expressed in breast cancer cell lines, its over-expression is associated with reduced cell invasion, increased apoptosis and reduced proliferation; miRNA-9 is thought to likely carry out its function by regulating SRPK1 activity." (PMID 35583632, 2022). "In summary, our study has revealed that in at least some breast cancer cells, loss of Tip60-mediated SRPK1 acetylation may ultimately lead to anti-apoptotic AS events and predict poor outcome following cisplatin treatment." (PMID 32461560, 2020). "SRPK1 has been previously implicated in the regulation of breast cancer metastasis." (PMID 32859889, 2020). "SRPK1 facilitates tumor progression in gastric and breast cancers by modulating RNA splicing and has also shown elevated expression in certain sarcoma subtypes, including synovial sarcoma." (PMID 40963856, 2025). "This has been observed in breast cancer cells, in which elevated SRPK1 reduces apoptosis through RBM4-regulated alternative splicing." (PMID 36895328, 2023). "In cisplatin-resistant breast cancer cells, reduced acetylation of SRPK1 by Tip60 increases its activity, favouring the expression of anti-apoptotic splice variants." (PMID 36895328, 2023). "SRPK1 expression is higher in breast cancer tissue compared to matched normal tissue, where expression is confined largely to ductal epithelium." (PMID 35583632, 2022). "In fact, SRPK1 has been proved to play critical roles in many different cancers, such as gastric cancer, lung cancer, breast cancer, prostate cancer, leukemia, hepatocellular carcinoma, and so on." (PMID 36038837, 2022). "For example, besides enhancing tumor cell proliferation, elevated SRPK1 can also attenuate apoptosis of breast cancer cells and esophageal squamous cell carcinomas." (PMID 35192432, 2022). "SRPK1 maintains RBM4 in the cytoplasm of breast cancer cells promoting preferential splicing of the anti-apoptotic myeloid leukaemia 1 (MCL-1) long isoform." (PMID 35583632, 2022). "SRPK1 plays a critical role in cancer bypassing apoptosis in several cancer types, such as colorectal cancer, breast cancer." (PMID 36038837, 2022). "Similar to what was observed in breast cancer cells, silencing of SRPK1 was found to inhibit MAPK/AKT signalling in colonic cancer cells." (PMID 35583632, 2022). "In breast cancer cells, cisplatin induced SRPK1 acetylation but in the corresponding resistant cells, it reduced acetylation yet increased phosphorylation and kinase activity of SRPK1, favouring the splicing of some anti-apoptotic variants." (PMID 32461560, 2020). "Among breast cancer cells, ER-negative breast cancer cells show higher expression of SRPK1, and knockdown of SRPK1 was reported to inhibit metastasis of ER-negative breast tumors in immunodeficient mice." (PMID 32106418, 2020). "We noted that cisplatin increased SRPK1 acetylation in a Tip60-dependent manner in breast cancer cells." (PMID 32461560, 2020).
breast cancer (continued). "To this end, we assessed SRPK1 expression using the US BioMax tissue microarray (#BC081120e) and found that SRPK1 expression was significantly higher in breast cancer samples, including TNBC samples, compared to normal adjacent tissue." (PMID 32859889, 2020). "We showed that like LIMK2, SRPK1 is overexpressed in several breast cancer subtypes compared to normal breast tissue." (PMID 32859889, 2020). "It was reported that elevated SRPK1 in breast cancer induces RNA binding motif 4 (RBM4) phosphorylation." (PMID 32106418, 2020). "Another example is SRPK1, encoding the splicing factor kinase SRSF protein kinase 1, which was highly expressed in basal breast cancer cells." (PMID 31206546, 2019). "Studies have found that SRPK1 expression was up-regulated in breast cancer, which correlated with poor outcome and preferential metastasis to the lungs and brain." (PMID 29262565, 2017). "In their recent study, van Roosmalen et al13 found that SRPK1 expression correlated with preferential metastasis of breast cancer to the lungs and brain." (PMID 27859253, 2017). "SRPK1 has been recently reported to be overexpressed in multiple cancers, including prostate cancer, breast cancer, lung cancer, and glioma." (PMID 27859253, 2017). "In breast cancer cells, increased levels of SRPK1 and the RNA binding protein RBM4 have been related to apoptosis resistance." (PMID 26273588, 2015). "In breast cancer, elevated SRPK1 activity reduces apoptosis through RBM4-regulated splicing events." (PMID 36895328, 2023). "Aberrant SRPK1 expression has been documented in cancers, breast cancer included." (PMID 37190199, 2023). "Inhibition of SRPK1 can reduce TAM resistance by suppressing BQ expression in ER +ve breast cancer." (PMID 37190199, 2023). "We identified seven papers which investigated the role of SRPK1 in breast cancer." (PMID 35583632, 2022). "SRPK1 silencing results in increased rates of apoptosis, and decreased phosphorylation of mitogen-activated protein kinase 3 (MAPK3), MAPK1 and protein kinase B (AKT) in breast cancer cell lines, suggesting a likely relationship between SRPK1 and AKT/MAPK signalling pathways." (PMID 35583632, 2022). "Tip60 acetylation of SRPK1 is a key step in the sensitisation of breast cancer cells to cisplatin." (PMID 35583632, 2022). "Controversially, SRPK1 is related to both chemotherapy sensitivity and resistance in many cancers, including lung, prostate, male germ cell, retinoblastoma, pancreas, colon, and breast cancer." (PMID 34193174, 2021). "Interestingly, a more prominent SRPK1 staining was detected in the nuclei of cisplatin-resistant breast cancer cells." (PMID 33808326, 2021). "In addition, SRPK1 is involved in the progression of many types of cancer, including breast cancer, prostate cancer, lung cancer, and melanoma, and the expression of its downstream targets are reported to be increased significantly." (PMID 34193174, 2021). "As a result, the resistant breast cancer cells could be re-sensitized by enhancing Tip60-mediated SRPK1 acetylation." (PMID 32461560, 2020). "Moreover, high expression of SRPK1 correlates with decreased metastasis-free survival of the patients with breast cancer and preferential metastasis to lung and brain." (PMID 32106418, 2020). "Hence, our study reveals a key role of SRPK1 in the development of cisplatin resistance in breast cancer cells and suggests a potential therapeutic avenue for overcoming chemotherapy resistance." (PMID 32461560, 2020). "To define the role of SRPK1 in breast cancer, we first asked whether SRPK1 is overexpressed in breast cancer." (PMID 32859889, 2020). "Furthermore, by analyzing several publicly available datasets of breast cancer mRNA expression datasets, we found that increased SRPK1 expression correlated with an increased incidence of metastasis, recurrence, and death in breast cancer patients." (PMID 32859889, 2020).
breast cancer (continued). "Indeed, our study reveals that SRPK1 acetylation has a significant impact on the splicing of key regulators of apoptosis in breast cancer cells." (PMID 32461560, 2020). "Taken together, we propose that SRPK1 acetylation could affect the cisplatin effectiveness via modifying the splicing of some key regulators of apoptosis in breast cancer cells." (PMID 32461560, 2020). "Next to the hnRNPs, the splice factor SRSF protein kinase 1 (SRPK1) was shown to be highly expressed in more aggressive basal breast cancer, correlating to less metastasis-free survival and specifically increased number of lung and brain metastases in patients." (PMID 31666932, 2019). "In breast cancer, SRPK1-induced alternative splicing plays a crucial role in oncogenesis as well." (PMID 31861708, 2019). "Furthermore, SRPK1 expression was investigated in relation to the breast cancer molecular subtypes and resistance to chemotherapy." (PMID 31861708, 2019). "The knockdown of SRPK1 significantly suppressed metastasis of breast cancer cells." (PMID 31206546, 2019). "Interestingly, although SRPK1 expression also appears to be increased in breast cancer 5, contemporary work seems to suggest an alternative mechanism of pathogenesis in this tumour type." (PMID 27859253, 2017). "Targeted inhibition of SRPK1 may exert some of its antitumor effects in breast cancer through altering the splice pattern and sensitivity to apoptotic signals." (PMID 29262565, 2017). "Furthermore, increased expression of SRPK1 and reduced expressions of the other three genes in basal-like breast cancer were also observed in the validation dataset." (PMID 29262565, 2017). "SRPK1 is upregulated in breast cancer and its expression level is proportional to the tumor grade." (PMID 19014521, 2008). "When the miR-101-5p-associated pathways in breast cancer were assessed using RNA-seq, a particular group of genes, HMGB3, ESRP1, GINS1, TPD52, SRPK1, VANGL1, and MAGOHB, were suggested to be associated with a poor prognosis of BC." (PMID 38132441, 2023). "In addition, it has been reported that SRPK1 could modulate cisplatin resistance and metastasis in breast cancer." (PMID 37190199, 2023). "Hence, by targeting the PTMs of SRPK1, we may alter the pre-mRNA AS of key regulators of apoptosis and modulate the cisplatin sensitivity of breast cancer cells." (PMID 32461560, 2020). "Therefore, targeting the PTMs and kinase activity of SRPK1 has the potential to re-sensitize breast cancer cells to chemotherapy, and this strategy has the advantage of being titratable and reversible as compared with other approaches, such as genetic manipulation." (PMID 32461560, 2020). "However, in breast cancer cells, whether SRPK1 can indeed be acetylated, whether the acetylation is mediated by Tip60 and whether this novel PTM of SRPK1 could lead to cisplatin resistance remain unknown." (PMID 32461560, 2020). "Moreover, others have linked more splicing factors such as the hnRNPs, SRSF1, SRPK1, and PTBP1 to breast cancer migration and metastasis formation, making it very interesting to systematically evaluate the role of splicing in breast cancer cell migration in future studies." (PMID 31278301, 2019). "Finally, we confirmed that SRPK1 inhibition also alters BRD4 splicing in breast cancer cells, a finding that may be of therapeutic significance in metastasis prevention." (PMID 30568163, 2018). "Therefore, inhibiting SRPK1 in ER +ve breast cancer could reduce TAM resistance." (PMID 37190199, 2023). "A migration screen based on a phagokinetic track assay identified SRPK1 as a determinant factor in breast cancer metastasis; and a separate study demonstrates that the LIM domain kinase 2 (LIMK2) promotes breast cancer metastasis through SRPK1 activation." (PMID 36895328, 2023). "SRPK1 and the splicing factor RNA-binding protein 4 (RBM4) are overexpressed in breast cancer tissue." (PMID 35583632, 2022).
breast cancer (continued). "We also found that similar to LIMK2, SRPK1 was overexpressed in TNBC compared to other breast cancer subtypes, and SRPK1 overexpression in breast cancer predicted increased incidence of cancer metastasis, recurrence, and death." (PMID 32859889, 2020). "Interestingly, in terms of molecular mechanism, SRPK1 seems to act heterogeneously, and has been reported to affect several processes in different cancers, e.g. angiogenesis in prostate and colon cancer, apoptosis in breast and colon cancer, and migration in breast cancer." (PMID 27859253, 2017). "Consistent with our results, analysis of multiple, publicly available breast cancer mRNA expression datasets also showed significantly higher SRPK1 mRNA expression in TNBC (ERBB2/ER/PR negative) samples compared to non-TNBC breast cancers." (PMID 32859889, 2020). "Additionally, SRPK1 and SRPK2 showed upregulated expression in CAC tissues compared with adjacent tissues, which is consistent with their expression patterns in acute myeloid leukemia, breast cancer, and pancreatic cancer." (PMID 33602301, 2021). "In addition to the dysregulation of MAPK pathways in colon and breast cancers owing to activity changes in MAP2K1 and MAP2K2, SRPK1 overexpression can also affect the splicing of the MAPK signaling pathway component PYK2 which, in turn, has been associated with cancer development." (PMID 26273588, 2015).